NLRX1 (NLR family member X1)
Diseases named in the same sentence as NLRX1 in open-access papers (continued):
Sharing a sentence is not in itself a finding about the gene and the disease.
myxoid liposarcoma (1 paper, 2016). A liposarcoma characterized by the presence of round non-lipogenic primitive mesenchymal cells and small signet ring lipoblasts within a myxoid stoma with a branching vascular pattern. "Interestingly, the human metadata analysis described in the current study found the greatest decrease in NLRX1 expression in myxoid liposarcoma." (PMID 27105514, 2016).
Nephropathy (1 paper, 2019). A nonspecific term referring to disease or damage of the kidneys. "An in vivo model more susceptible to nephropathy may be useful in determining whether reduced NLRX1 expression in DN elicits a functional effect." (PMID 30908533, 2019).
neutropenia (1 paper, 2020). A decrease in the number of neutrophils found in the blood. "Based on these results we conclude loss of Nlrx1 increases mortality in the steroid and neutropenia models of IPA for both isolates." (PMID 32956405, 2020).
non-alcoholic fatty liver disease (1 paper, 2025). "Deletion of NLRX1 increased mitochondrial fatty acid-dependent oxidative phosphorylation (OXPHOS), decreased glycolysis in hepatocytes and protected against diet-induced metabolic syndrome and non-alcoholic fatty liver disease (NAFLD) development." (PMID 40536683, 2025).
Optic neuropathy (1 paper, 2025). "Additionally, we observed an unexpected significant decrease in RGC density in IgHMOGNlrx1−/− control mice compared to IgHMOG Nlrx1+/+ control mice, suggesting that in the setting of NLRX1 loss and associated immune dysregulation, anti-MOG immunoglobulins can lead to some degree of optic neuropathy." (PMID 39875919, 2025). "TCRMOGNlrx1−/− mice showed a significant loss of RGCs compared to TCRMOGNlrx1+/+ mice, suggesting that in the absence of NLRX1, MOG-specific T-cells can also lead to optic neuropathy independent from spinal cord pathology." (PMID 39875919, 2025).
pancreatic cancer (1 paper, 2023). "Our data suggest NLRX1 serves in a protective capacity against several cancer-associated biological processes in pancreatic cancer cells, including proliferation, evading cell death, migration, ROS signaling, and dysregulated mitochondrial function." (PMID 37342194, 2023). "Together, our data identify multiple signaling pathways impacted by alterations in NLRX1 expression associated with pancreatic cancer." (PMID 37342194, 2023). "Here, we define roles for NLRX1 in regulating critical hallmarks of pancreatic cancer using both gain-of-function and loss-of-function studies in murine Pan02 cells." (PMID 37342194, 2023). "Together, these data demonstrate that NLRX1 diminishes cancer-associated biological functions in pancreatic cancer cells and establishes a role for this unique NLR in tumor suppression." (PMID 37342194, 2023). "Here, we have established through in vitro assays and transcriptomics analysis that NLRX1 in murine pancreatic tumor cells is protective against cancer-associated phenotypes and likewise that the loss of NLRX1 augments cancer-associated phenotypes." (PMID 37342194, 2023). "These outcomes suggest that further exploration of NLRX1 in pancreatic cancer, such as in vivo models of pancreatic cancer, is warranted." (PMID 37342194, 2023). "Utilizing additional murine cell lines and human pancreatic cancer cell lines for future in vitro studies similar to those conducted here would also further enhance our understanding of NLRX1 in pancreatic cancer." (PMID 37342194, 2023). "To elucidate what general functions NLRX1 performs when it is expressed in pancreatic cancer cells, we generated Pan02 cells to either overexpress or knockdown NLRX1, as well as their respective controls (Pan02OE, Pan02OE-CTL, Pan02KD, Pan02KD-CTL)." (PMID 37342194, 2023). "Together, these data indicate a significant role for NLRX1 in many pathways and processes important to pancreatic cancer." (PMID 37342194, 2023). "Because pancreatic cancer is typically a highly immunosuppressive tumor type and NLRX1 is best characterized for its roles in modulating immune system function, immunomodulation by NLRX1 is certainly of interest in this model." (PMID 37342194, 2023). "Through upregulating Csf2, NLRX1 is potentially helpful in promoting immune recognition of pancreatic tumors." (PMID 37342194, 2023). "In conclusion, we have characterized several phenotypes in murine Pan02 pancreatic tumor cells that are impacted by NLRX1." (PMID 37342194, 2023). "To date, the role of NLRX1 in pancreatic cancer is undefined and unexplored." (PMID 37342194, 2023). "The work presented here demonstrates that NLRX1 functions as a tumor suppressor in Pan02 cells and provides insight into mechanisms likely regulated by this unique pattern recognition receptor in the context of pancreatic cancer." (PMID 37342194, 2023). "Likewise, our transcriptomics analysis revealed an important role for NLRX1 in pancreatic cancer cells through NF-κB, AKT, MAPK, and IL-6 signaling and highlights these pathways as likely mechanisms by which NLRX1 asserts its protective qualities in Pan02 cells." (PMID 37342194, 2023). "Aberrant IL-6 and IL-18 levels both create a tumor microenvironment that is favorable for the tumor cells by promoting survival and establishing an immunosuppressive environment, suggesting that NLRX1 may protect against pancreatic tumors through regulating inflammation and inflammatory cytokines." (PMID 37342194, 2023). "NLRX1 is a unique, understudied member of the Nod-like Receptor (NLR) family of pattern recognition receptors that regulates a variety of biological processes that are highly relevant to pancreatic cancer." (PMID 37342194, 2023).
pancreatic cancer (continued). "Interestingly, many of the pathways identified here are consistent with pathways identified in previous studies of NLRX1, including PI3K-AKT, MAPK, EGFR, NF-κB, and IL-6 signaling, and these pathways are all important to the initiation and progression of pancreatic cancer." (PMID 37342194, 2023).
periodontitis (1 paper, 2019). An acute or chronic inflammatory process that affects the tissues that surround and support the teeth. "NLRX1 expression is increased in human adult periodontitis patient samples." (PMID 31681307, 2019).
prostate carcinoma (1 paper, 2026). A carcinoma that arises from epithelial cells of the prostate gland. "This study explored the role of NLRX1 in prostate cancer (PCa), examining its impact on cell proliferation, apoptosis, migration, invasion, and tumor progression, as well as associated molecular mechanisms." (PMID 42088413, 2026).
pyelonephritis (1 paper, 2021). An inflammatory process affecting the kidney. "They observed that absence of NLRX1 results in decreased bacterial clearance, but has no impact on the number of circulating leukocytes or immune cells in the bladder of mice with pyelonephritis caused by Escherichia coli." (PMID 33525671, 2021).
Splenomegaly (1 paper, 2016). Abnormal increased size of the spleen. "The increased urethane sensitivity observed in the Nlrx1−/− mice was directly correlated with splenomegaly." (PMID 27105514, 2016).
squamous cell carcinoma of the skin (1 paper, 2016). "For example, at the extremes, NLRX1 was found to be up-regulated 2.72 fold in squamous cell carcinoma of the skin compared to normal skin, while being down-regulated 8.1 fold in high grade myxoid liposarcoma tumors compared to normal adipose tissue." (PMID 27105514, 2016).
triple-negative breast carcinoma (1 paper, 2022). An invasive breast carcinoma which is negative for expression of estrogen receptor (ER), progesterone receptor (PR), and human epidermal growth factor receptor 2 (HER2). "Specifically, NLRX1 depletion in MDA-MB-231 cells (a triple-negative breast cancer cell line) decreased the organization and activity of OXPHOS complexes, affecting OXPHOS-dependent cell proliferation and the migration of triple-negative breast cancer cells." (PMID 34697412, 2022).
Type 1 Diabetes (1 paper, 2019). "For this reason, we investigated the role of NLRX1 in the development of DN in a Type 1 Diabetes mouse model." (PMID 30908533, 2019).
urinary tract infection (1 paper, 2021). "They concluded that NLRX1 can be involved in urinary tract infections, however, it does not affect directly the functions of granulocytes and monocytes." (PMID 33525671, 2021).
infection (24 papers, 2011 to 2025). The state of being infected such as from the introduction of a foreign agent such as serum, vaccine, antigenic substance or organism. "NLRX1 also negatively regulates inflammation during infection with Kaposi’s sarcoma-associated herpes virus (KSHV)." (PMID 40356929, 2025). "Using Nlrx1−/− mice, IAV infection resulted in a significant increase in IFN signaling and the production of IFN‐β compared to wild‐type mice, leaving Nlrx1−/− more susceptible to infection by increasing airway epithelial cell denuding, obscured small airways, and IL‐6 production." (PMID 39878363, 2025). "Interestingly, at 8 hours post-infection, Nlrx1-deficient cells clustered together with males with LgyLRV1+ infection, while at 24 hours this clustering occurred in all conditions except treatment with poly I:C." (PMID 35651602, 2022). "Taken together, NLRX1-mediated microglial immunosuppression might contribute to susceptibility to infection." (PMID 35414088, 2022). "Supporting the male-like behavior of Nlrx1-deficient female cells, we could observe that at 24 hours post-infection, in all condition except with poly I:C treatment, the Nlrx1-/- female BMDMs clustered more closely to the WT and Nlrx1-deficient male BMDMs than to the WT female." (PMID 35651602, 2022). "Our previous study discovered that the NLRX1 protein, predominantly in mitochondria, exhibited significant up−regulation following PAstV−4 infection." (PMID 38891045, 2024). "This study first explored the role of NLRX1 on intestinal mucosal barrier injury induced by PAstV−4 infection." (PMID 38891045, 2024). "In summary, this study preliminarily explains that NLRX1 plays an important role in the disruption of intestinal mucosal function triggered by PAstV–4 infection via the ERK/MLC pathway." (PMID 38891045, 2024). "Real-time PCR analysis confirmed the significant up-regulation of NLRX1 expression at 24 h post-infection." (PMID 38891045, 2024). "Building upon our prior findings indicating that PAstV/SH/2022/CM1 infection up-regulated the expression of NLRX1 in PK15 cells, we sought to confirm this result in the intestinal epithelial cells during PAstV infection." (PMID 38891045, 2024). "Subsequently, screening and identification of the interacting proteins of NLRX1 will be carried out so as to resolve the specific mechanism of NLRX1 in the dysfunction of the intestinal mucosal barrier induced by PAstV−4 infection." (PMID 38891045, 2024). "In conclusion, the data in this study revealed that NLRX1 plays a vital role in destruction of the intestinal mucosal barrier induced by PAstV–4 infection via mitophagy." (PMID 38891045, 2024). "In this study, we found that PAstV−4 infection up−regulated the expression of NLRX1 and LC3II, while silencing the expression of NLRX1 inhibited PAstV replication and mitophagy." (PMID 38891045, 2024). "In this study, we confirmed that PAstV–4 infection significantly up-regulated NLRX1 and mitophagy in Caco–2 cells, while the silencing of NLRX1 or the treatment of mitophagy inhibitor 3–MA inhibited PAstV–4 replication." (PMID 38891045, 2024). "For example, NLRX1 negatively regulates infection-induced IFN-I signaling and IL-6 production in primary MEFs by inhibiting the interaction between MAVS and RIG-I." (PMID 37528226, 2023). "Based on the in vivo data, the role of NLRX1 in the regulation of inflammation and infection was highly dependent on sex." (PMID 35651602, 2022). "To investigate the role of NLRX1, we used an experimental murine model based on a protozoan parasite, Leishmania guyanensis (Lgy), inducing cutaneous lesions at the site of the infection." (PMID 35651602, 2022). "To better understand the role of NLRX1 in our model system of infection, we first performed a transcriptomics analysis of infected female BMDMs." (PMID 35651602, 2022).
infection (continued). "Upon HIV-1 or DNA virus (HSV, vaccinia virus) infection, NLRX1 disrupts STING-TBK1 signaling, which mediates IFN production, and thus facilitates viral replication in myeloid cells." (PMID 33525671, 2021). "In terms of mechanism, NLRX1 can modulate mROS during infection possibly through interaction with UQCRC2, a matrix-facing protein of the respiratory chain complex III (bc1 complex)." (PMID 34299310, 2021). "In airway epithelial cells, it was shown that NLRX1 is expressed in both the cytoplasm and at the apical surface; however, after infection it translocates to the mitochondria." (PMID 33525671, 2021). "ROS have either protective or detrimental effects upon infections, and the ability of NLRX1 to modulate mtROS production can also be hijacked by many invading pathogens." (PMID 33525671, 2021). "For example, it was published that in Rhesus monkeys simian immunodeficiency virus (SIV) triggers NLRX1 expression in the beginning of the infection to facilitate its own replication." (PMID 33525671, 2021). "During infection, NLRX1 interacts with MAVS to promote its ubiquitination and subsequent degradation, while the depletion of NLRX1 stabilises the MAVS-RIG-1 interaction and constitutively activates MAVS." (PMID 34386501, 2021). "Experimental validation of computational modeling predictions demonstrated that NLRX1-KO BMDMs produced significantly more IFNγ and ROS compared to the wild type cells after infection." (PMID 33525671, 2021). "NLRX1 attenuates several inflammatory pathways and modulates cellular processes such as autophagy and mitochondrial function following infection or injury." (PMID 33344269, 2020). "(2008), four independent groups generated mice models to further investigate the role of NLRX1 in infection." (PMID 33344269, 2020). "Of these 7 cytokines/chemokines, only 4 were expressed in wild type at relatively low concentrations, while 3 (CCL20, CCL17, CXCL1) appeared to be uniquely expressed in Nlrx1-/- mice at this early stage of infection." (PMID 32956405, 2020). "This is clearly exemplified in the NLRX1-dependent increase in ROS production observed during infection versus the NLRX1-dependent decrease in ROS production under ischemic conditions." (PMID 30908533, 2019). "As expected, the number of GcAV-positive cells in NLRX1 KO cells was higher during the early stage of infection (30–120 min) compared to that in wild-type cells." (PMID 30488027, 2018). "As expected, autolysosome formation was significantly promoted in NLRX1 KO cells compared to that in HeLa wild-type cells at 120 and 240 min after infection." (PMID 30488027, 2018). "Our transcriptomic profiling demonstrates that macrophages treated with H. pylori have significantly repressed Nlrc3 and Nlrx1 transcripts, especially early post-infection; a finding further validated by qRT-PCR along with sustained and late-wave genes." (PMID 26367386, 2015). "Second, sustained inflammatory mediators are required for the induction of NLRX1 expression during infection." (PMID 26367386, 2015). "Nlrx1-/- mice experienced significantly lower gastric bacterial loads when compared to their wild-type counterparts beginning 21 days post infection." (PMID 26367386, 2015). "A recently discovered protein, Nlrx1, regulates inflammatory and cell death responses during infection." (PMID 25540124, 2014). "Emerging evidence suggests that NLRX1 may also serve as a key regulator of inflammation and metabolic processes during infection, further contributing to its complex role in immunity." (PMID 40356929, 2025). "This study also suggested that antiviral gene expression was similar between lung homogenates of wild-type and Nlrx1-/- mice following infection with influenza A virus and extended these findings to include Nlrx1-/- bone marrow derived macrophages (BMDMs) and MEFs infected with SeV." (PMID 40356929, 2025). "Until now, the specific role of NLRX1 in AstVs infection was scarcely known." (PMID 38891045, 2024).